GSN (gelsolin)
Description:
Calcium-regulated, actin-modulating protein that binds to the plus (or barbed) ends of actin monomers or filaments, preventing monomer exchange (end-blocking or capping). It can promote the assembly of monomers into filaments (nucleation) as well as sever filaments already formed. Plays a role in ciliogenesis.
Synonyms: ADF; DKFZp313L0718; AGEL; AMYLD4
Tractability: Small molecule: a structure with a bound ligand is known. Antibody: its Gene Ontology location is reachable by antibodies, with high confidence; UniProt places it where antibodies can reach, with medium confidence; UniProt predicts a signal peptide or a membrane-spanning region. PROTAC: ubiquitination databases record sites on it; its protein half-life has been measured.
Gene: Protein-coding gene on chromosome 9 (121,201,324 to 121,334,721, forward strand). Ensembl gene ENSG00000148180.
Subcellular location: Cytoplasm, cytoskeleton (Isoform 2); Secreted (Isoform 1)
Subcellular location (Human Protein Atlas): Actin filaments; Predicted to be secreted
Pathways (Reactome):
Immune System: Neutrophil degranulation
Metabolism of proteins: Amyloid fiber formation
Programmed Cell Death: Caspase-mediated cleavage of cytoskeletal proteins
Sensory Perception: Sensory processing of sound by outer hair cells of the cochlea
Gene Ontology:
Molecular function: actin binding; calcium ion binding; myosin II binding; phosphatidylinositol 3-kinase catalytic subunit binding; protein binding; phosphatidylinositol-4,5-bisphosphate binding; actin filament binding
Biological process: actin filament capping; actin filament depolymerization; actin filament organization; actin filament polymerization; actin filament severing; amyloid fibril formation; cilium assembly; hepatocyte apoptotic process; host-mediated suppression of symbiont invasion; positive regulation of actin nucleation; positive regulation of gene expression; positive regulation of keratinocyte apoptotic process; protein destabilization; regulation of establishment of T cell polarity; regulation of plasma membrane raft polarization; regulation of receptor clustering; renal protein absorption; striated muscle atrophy; actin polymerization or depolymerization; barbed-end actin filament capping; cardiac muscle cell contraction; central nervous system development; phagocytosis, engulfment; positive regulation of protein processing in phagocytic vesicle; relaxation of cardiac muscle; and 3 more
Cellular component: actin cap; actin cytoskeleton; blood microparticle; cortical actin cytoskeleton; cytoplasm; cytosol; extracellular exosome; extracellular region; focal adhesion; nucleus; plasma membrane; sarcoplasm; ficolin-1-rich granule lumen; secretory granule lumen; cytoskeleton; lamellipodium; phagocytic vesicle
Genetic constraint (gnomAD): Loss-of-function variants: 46 observed, 74.67 expected, observed/expected ratio (o/e) 0.62, 90% interval 0.49 to 0.79. The upper end of that interval is the gene's LOEUF score, 0.79, which puts it in group 3 of 6, group 1 being the genes least tolerant of losing a copy. Missense variants: 794 observed, 951.5 expected, observed/expected ratio (o/e) 0.83, 90% interval 0.79 to 0.88. Synonymous variants: 350 observed, 392 expected, observed/expected ratio (o/e) 0.89, 90% interval 0.82 to 0.98.
Homologues: Orthologues: chimpanzee GSN (99% identical), macaque GSN (99% identical), pig GSN (96% identical), guinea pig GSN (95% identical), dog GSN (95% identical), mouse Gsn (95% identical), rat Gsn (95% identical), rabbit GSN (93% identical), zebrafish gsna (74% identical), tropical clawed frog gsn (73% identical), zebrafish gsnb (67% identical), Drosophila melanogaster Gel (38% identical), and 1 more. Paralogues in human: SCIN (59% identical), VIL1 (50% identical), AVIL (47% identical), VILL (40% identical), FLII (29% identical), SVIL (29% identical), CAPG (23% identical).
Diseases named in the same sentence as GSN in open-access papers:
GSN is named in the same sentence as 285 diseases in open-access papers, as found by Europe PMC text mining. Sharing a sentence is not in itself a finding about the gene and the disease. The quoted sentences say what the papers report.
amyloidosis (50 papers, 2005 to 2026). A disorder characterized by the localized or diffuse accumulation of amyloid protein in various anatomic sites. "We report a gelsolin amyloidosis in a 58-year-old man with nephrotic syndrome and slowly progressive kidney dysfunction, associated with a gelsolin gene mutation (c.480C > A, p.Asn160Lys)." (PMID 42232968, 2026). "Aggregation of aberrant fragment of plasma gelsolin, AGelD187N, is a crucial event underlying the pathophysiology of Finnish gelsolin amyloidosis, an inherited form of systemic amyloidosis." (PMID 38944121, 2024). "In this study, we report high-affinity antigen-binding fragment (Fab) antibody fragments against the monomeric gelsolin amyloidogenic peptide AGelD187N, which is aberrantly formed in the Finnish variant of gelsolin amyloidosis." (PMID 38944121, 2024). "We conclude that this study provides the first demonstration of high-affinity binders and aggregation inhibitors to the aberrant amyloidogenic AGelD187 peptide, which causes gelsolin amyloidosis." (PMID 38944121, 2024). "In this study, we have described the discovery of high-affinity antibody fragments that bind to different epitopes of monomeric AGelD187N, an aberrant amyloidogenic fragment of plasma gelsolin that causes hereditary gelsolin amyloidosis." (PMID 38944121, 2024). "Aggregation of the gelsolin protein fragment is the hallmark of the hereditary systemic disease gelsolin amyloidosis." (PMID 37590229, 2023). "We describe a novel mutation of GSN gene, p.Glu580Lys, associated with gelsolin amyloidosis in six members of a two-generation family, who exhibited lattice corneal dystrophy, loose facial skin and irregular heart rhythm." (PMID 33499149, 2021). "In one patient we reported optic nerve impairment, which is possibly a novel feature associated with gelsolin amyloidosis." (PMID 33499149, 2021). "Gelsolin mutations cause amyloidosis, characterised by the toxic accumulation of protein aggregates, which can lead to an inclusion body myositis (IBM)-like phenotype with necrotic and centronuclear split fibres." (PMID 34162956, 2021). "For decades, G2, which hosts the classic p.Asp214Asn or p.Asp214Tyr mutations, was thought to be the only domain associated with gelsolin amyloidosis." (PMID 33499149, 2021). "The novel GSN variant p.Glu580Lys is associated with the typical gelsolin amyloidosis phenotype, including its hallmark, the corneal lattice dystrophy." (PMID 33499149, 2021). "Here we report clinical and histopathological features of gelsolin amyloidosis associated with a novel GSN variant p.Glu580Lys." (PMID 33499149, 2021). "Plasma GSN levels were associated with several disorders such as amyloidosis, inflammation, and oncogenic transformation." (PMID 34501327, 2021). "The p.Glu580Lys is associated with corneal dystrophy, strengthening the association of the fifth domain of gelsolin protein with the typical amyloidosis phenotype." (PMID 33499149, 2021). "The C. elegans-based assay was also applied to investigate the mechanisms underlying gelsolin amyloidosis, a neglected familial amyloidosis caused by pathological aggregation and peripheral deposition of proteolytic fragments of plasma gelsolin." (PMID 33187241, 2020). "Conversely, the presence of mutations in plasma gelsolin is known to be directly related to a rare form of amyloidosis, hereafter referred as AGel amyloidosis (AGel, OMIM reference number 105120)." (PMID 29069428, 2018). "Finnish gelsolin amyloidosis is caused by a mutation in the gene coding for gelsolin (GSN), which is located on chromosome 9 (Kwiatkowski, Westbrook, Bruns, & Morton, 1988)." (PMID 30417985, 2018).
amyloidosis (continued). "The gelsolin amyloidosis patients with the Finnish mutation will experience a triad of ophthalmological, neurological and dermal symptoms as a cause of gelsolin fragment accumulation in the basement membrane of the skin, blood vessel walls, eyes and peripheral nervous system." (PMID 37590229, 2023). "GSN, the causative protein in Finnish amyloidosis, was associated with Lobar ICH." (PMID 36936603, 2022). "Mutations in the GSN gene have been linked to familial amyloidosis of Finnish type (FAF) or gelsolin amyloidosis [MIM#105120], a rare, autosomal dominant hereditary amyloid polyneuropathy, mainly characterized by progressive cranial neuropathies, corneal lattice dystrophy, and sensory neuropathy." (PMID 32824961, 2020). "Moreover, mutations in the gelsolin gene are directly responsible for gelsolin amyloidosis (GA) with 100% penetrance." (PMID 27633054, 2016). "Experimentally, a transgenic mouse model of Finnish-type familial amyloidosis associated with gelsolin amyloidosis in skeletal muscle (with the gelsolin transgene under the control of a muscle specific promoter), is associated with amyloid deposits with foci of mononuclear cell infiltration." (PMID 25579751, 2015). "Another feature differentiating gelsolin amyloidosis from other protein misfolding diseases is that the amyloidogenic AGelD187N monomer does not have any physiological role in the body, making it a suitable therapeutic target for neutralization." (PMID 38944121, 2024). "As for most amyloid diseases, there is only symptomatic treatment available for gelsolin amyloidosis, and a disease-modifying treatment would be highly desirable." (PMID 38944121, 2024). "Hereditary amyloidosis comprises more than 30 subtypes, including TTR, ApoA-I, ApoA-II, gelsolin, lysozyme amyloidosis, cystatin C amyloidosis (ACys), fibrinogen Aα-chain, β2-microglobulin, ApoC2-II, and ApoC39." (PMID 39152105, 2024). "In contrast, Finnish gelsolin amyloidosis has a straightforward disease pathophysiology with 100% penetrance and early onset of disease." (PMID 38944121, 2024). "As with other protein misfolding diseases, there is an urgent need for efficient disease-modifying treatment for gelsolin amyloidosis." (PMID 37590229, 2023). "In this work we have described a practical and drug discovery suitable approach to study in vitro the aggregation kinetics of the main amyloidogenic polypeptide in Finnish gelsolin amyloidosis, the 70-residue gelsolin fragment AGelD187N 173–242." (PMID 37590229, 2023). "Lattice corneal dystrophy type II should raise the suspicion of hereditary gelsolin amyloidosis, especially if accompanied by peripheral facial nerve palsy and peripheral neuropathy." (PMID 34206500, 2021). "Two members of a family (F.4.1; F.4.2) with hereditary gelsolin amyloidosis had facial paralysis, fasciculations, and weakness of other bulbar muscles." (PMID 34103343, 2021). "Only a few hundred cases of patients with gelsolin amyloidosis have been described in the literature, mostly of Finnish origin harboring the pathogenic variant p.Asp214Asn in the domain G2." (PMID 33499149, 2021). "Osmotic disruption has been applied to the anti-gelsolin VHH Nb11 designed for the potential treatment of hereditary gelsolin amyloidosis, an autosomal dominantly inherited amyloid disorder." (PMID 33007904, 2020). "Another protein misfolding disease is gelsolin amyloidosis, an autosomal dominantly inherited affliction that leads to a plethora of neurological, ophthalmological and dermatological symptoms." (PMID 33322697, 2020). "AAV-9 delivery of Nb11-FAF-1 in a gelsolin amyloidosis mouse model resulted in a significant drop in aberrant gelsolin fragments in heart and skeletal muscles." (PMID 33322697, 2020). "In hereditary gelsolin amyloidosis, also called familial amyloidosis Finnish type (FAF), a mutation in the GSN gene on chromosome 9 causes gelsolin to be abnormally cleaved, generating several small fragments with amyloidogenic properties." (PMID 31847365, 2019).
amyloidosis (continued). "First manifestations of gelsolin amyloidosis are lattice dystrophy of the cornea and amyloid depositions found in eye elements: the sclera, the conjunctiva, nerves, and vessels." (PMID 25352156, 2016). "More data about gelsolin in NC derivatives comes from studies concerning a very rare autosomal dominant disease: gelsolin amyloidosis known also as the familial amyloidosis of Finnish type (FAF)." (PMID 25352156, 2016). "The effect of homozygosity on phenotype has been reported for patients with hereditary transthyretin or gelsolin amyloidosis, but this is the first report for AFib amyloidosis." (PMID 26199771, 2015). "In gelsolin (AGel) amyloidosis, homozygotes have been reported to show earlier onset and more severe clinical manifestations than heterozygotes, explained by the lethal effects of the mutant genes." (PMID 26199771, 2015). "Other dominant hereditary forms of amyloidosis include apolipoprotein AI- and II-, gelsolin-, cystatin C-, lysozyme-, and fibrinogen A-related diseases, all of which are extremely rare and have relatively early onset and distinct geographical locations." (PMID 24138840, 2013). "Mutant gelsolin isoforms lead to misfolding and the perivascular amyloid fibril deposition in Finnish type cerebrovascular amyloidosis." (PMID 16321154, 2005). "The diagnosis of gelsolin amyloidosis was confirmed by mass spectrometry and immunohistochemistry." (PMID 42232968, 2026). "Due to the simple pathophysiology and accessibility of the amyloidogenic peptides, gelsolin amyloidosis could serve as an optimal model disease to test the still not fully validated amyloid hypothesis prevailing in the field of neurodegenerative diseases." (PMID 38944121, 2024). "Also, apolipoprotein A-I, II and IV amyloidosis, fibrinogen alpha chain and gelsolin amyloidosis have been reported." (PMID 39408996, 2024). "Based on their etiology, the proteins that determine this pathology are light chain amyloidosis (AL), transthyretin amyloidosis (ATTR), serum amyloid A amyloidosis (AA), apolyprotein A amyloidosis (AApo AI/II), fibrinogen amyloidosis (AFib) and gelsolin amyloidosis (AGel)." (PMID 36611375, 2022). "HA includes Hereditary amyloidogenic transthyretin (hATTRv), amyloidosis derived from a fibrinogen variant (AFib), that is the most frequent HA in Northern Europe, variants of apolipoproteins (AI, AII, C-II, CIII), gelsolin (AGel), and lysozyme (ALys)." (PMID 33801069, 2021). "Hereditary gelsolin amyloidosis is a rare subtype of hereditary systemic amyloidosis." (PMID 34651091, 2021). "Frequent complications of gelsolin amyloidosis are chronic open-angle glaucoma and cataracts." (PMID 34206500, 2021). "Autopsy examination of the eyes of patients with gelsolin amyloidosis revealed ocular amyloid deposits in the conjunctiva, sclera, perineurium of the ciliary nerves, walls of the ciliary vessels, optic nerve sheaths, stroma of the ciliary body and along the choriocapillaris." (PMID 33499149, 2021). "There are no reports of a sporadic or wild-type form of gelsolin amyloidosis; hence, mutations are critical." (PMID 34206500, 2021). "There was a family history of hereditary gelsolin amyloidosis." (PMID 34651091, 2021). "Gelsolin and keratoepithelin are other proteins that, when mutated, are responsible for a systemic amyloid disease with significant ocular manifestations that not infrequently appear before systemic involvement." (PMID 34206500, 2021). "The mutation p.Glu580Lys described in the present study is also located in the G4:G5 interface and associated with the typical phenotype and supports the observation that mutations at various locations are able to produce classic phenotype of gelsolin amyloidosis and a common pathogenetic pathway." (PMID 33499149, 2021). "In this study, we report a case of Finnish gelsolin amyloidosis (FGA) in a Chinese family." (PMID 30417985, 2018). "Homozygosity has only been reported for hereditary gelsolin and transthyretin amyloidosis." (PMID 26199771, 2015).
amyloidosis (continued). "Moreover, the overexpression of the proteolytic fragments of mutant (D187N/Y) plasma gelsolin (familial Finnish amyloidosis) also leads to muscle weakness, the appearance of vacuoles and an increase in proteasome and autophagy markers." (PMID 25579751, 2015). "Progress in alleviating tissue damage and clinical symptoms by inhibiting aggregation in gelsolin amyloidosis could encourage and guide the work among more complex protein misfolding diseases, which pose an enormous burden on innumerable individuals and society." (PMID 38944121, 2024). "However, considering that amyloid deposition in gelsolin amyloidosis is observed in multiple organs and tissues, the number of AGelD187N peptides emerging in the patient's body could be large." (PMID 38944121, 2024). "Optic neuropathy or other optic nerve involvement has not been previously reported in association with gelsolin amyloidosis, however, bilateral consecutive anterior ischemic optic neuropathy has been documented in patients with the sporadic light-chain amyloidosis." (PMID 33499149, 2021). "Conversely, the cytoplasmic isoform of gelsolin could be the etiological agent of this amyloidosis." (PMID 29069428, 2018). "More recently, 99mTc-labeled Nbs targeting amyloidogenic peptides were used to visualize amyloidogenic gelsolin deposition by SPECT/CT, in a mouse model of gelsolin amyloidosis." (PMID 33353213, 2020). "In brain gelsolin has many roles including modulating NMDA receptors, altering dendritic spines, being highly expressed by oligodendrocytes, and modulating amyloidosis." (PMID 24007566, 2013). "Gene therapy would be an elegant way to deal with a monogenic disorder such as gelsolin amyloidosis, but the technology is not yet fully established." (PMID 38944121, 2024). "The epitope-specific anti-AGelD187N Fabs can be exploited not only in fundamental research on gelsolin amyloidosis but also in developing currently lacking disease-modifying treatments and diagnostic tools for the disease." (PMID 38944121, 2024). "The assay presented in this study now enables the screening of possible anti-aggregational hit compounds against gelsolin amyloidosis, a severe inherited disease currently with no cure." (PMID 37590229, 2023). "Contrary to the typical phenotype, facial nerve palsy was not frequent and the proband exhibited consecutive optic neuropathy, not yet reported in gelsolin amyloidosis." (PMID 33499149, 2021). "Optic neuropathy has not yet been reported as a feature of gelsolin amyloidosis but was a prominent clinical feature in the patient II-1, who presented to the Eye Hospital at the age of 63 years with optic nerve edema and contralateral optic nerve atrophy." (PMID 33499149, 2021). "Hereditary transthyretin amyloidosis (hATTR) with polyneuropathy (formerly known as Familial Amyloid Polyneuropathy (FAP)) is an endemic amyloidosis involving the harmful aggregation of proteins, most commonly transthyretin (TTR) but sometimes also apolipoprotein A-1 or gelsolin." (PMID 38927056, 2024). "However, if gelsolin preserves these protective properties in gelatinous drop-like corneal dystrophy and hereditary gelsolin, amyloidosis in the eye has not been proved yet." (PMID 32566091, 2020). "There are no data on hereditary amyloidosis other than FAP in Sweden, except that an expert review stated that gelsolin and apolipoprotein-related familial patients have been identified." (PMID 24138840, 2013).